HNRNPA3 (heterogeneous nuclear ribonucleoprotein A3)
Description:
Plays a role in cytoplasmic trafficking of RNA. Binds to the cis-acting response element, A2RE. May be involved in pre-mRNA splicing.
Synonyms: HNRPA3; 2610510D13Rik; D10S102; FBRNP
Tractability: PROTAC: UniProt records ubiquitination sites on it; ubiquitination databases record sites on it; its protein half-life has been measured.
Gene: Protein-coding gene on chromosome 2 (177,212,587 to 177,226,106, forward strand). Ensembl gene ENSG00000170144.
Subcellular location: Nucleus
Subcellular location (Human Protein Atlas): Nucleoplasm
Pathways (Reactome):
Metabolism of RNA: Processing of Capped Intron-Containing Pre-mRNA; mRNA Polyadenylation; mRNA Splicing - Major Pathway
Disease: Dengue Virus-Host Interactions
Gene Ontology:
Molecular function: protein binding; RNA binding; mRNA 3'-UTR binding; nucleic acid binding
Biological process: mRNA splicing, via spliceosome
Cellular component: catalytic step 2 spliceosome; nucleoplasm; nucleus; ribonucleoprotein complex
Genetic constraint (gnomAD): Loss-of-function variants: 2 observed, 38.85 expected, observed/expected ratio (o/e) 0.0515, 90% interval 0.02 to 0.16. The upper end of that interval is the gene's LOEUF score, 0.16, which puts it in group 1 of 6, group 1 being the genes least tolerant of losing a copy. Missense variants: 153 observed, 378.14 expected, observed/expected ratio (o/e) 0.4, 90% interval 0.35 to 0.46. Synonymous variants: 137 observed, 123.65 expected, observed/expected ratio (o/e) 1.11, 90% interval 0.96 to 1.28.
Homologues: Orthologues: guinea pig HNRNPA3 (97% identical), rat Hnrnpa3 (92% identical), zebrafish hnrnpa0a (49% identical), zebrafish hnrnpa0b (48% identical), zebrafish hnrnpa0l (46% identical). Paralogues in human: HNRNPA1 (71% identical), HNRNPA1L3 (67% identical), HNRNPA2B1 (67% identical), HNRNPA1L2 (66% identical), HNRNPA0 (35% identical), MSI2 (31% identical), HNRNPD (31% identical), MSI1 (30% identical), HNRNPDL (29% identical), HNRNPAB (29% identical), NUCLEOLIN (27% identical), DAZAP1 (27% identical), and 24 more.
Diseases named in the same sentence as HNRNPA3 in open-access papers:
HNRNPA3 is named in the same sentence as 21 diseases in open-access papers, as found by Europe PMC text mining. Sharing a sentence is not in itself a finding about the gene and the disease. The quoted sentences say what the papers report.
viral infection (3 papers, 2015 to 2024). "Of these, only a few parent genes code for proteins that are known to have a role in viral infection, such as HNRNPA3/HNRNPA1." (PMID 26426037, 2015). "However, the research on HNRNPA3 is mainly focused on its role in disease occurrence, but there is an absence of research on its function in virus infection." (PMID 38259103, 2024).
COVID-19 (2 papers, 2023 to 2024). A disease caused by infection with severe acute respiratory syndrome coronavirus 2. "Therefore, prospective studies are needed to collect human lung tissue samples before SARS-CoV-2 infection and determine whether pre-infection levels of Dicer, XPO5, SRSF3, and hnRNPA3 are associated with COVID-19 severity." (PMID 39138195, 2024). "Herein, we show that decreased RNAi component (Dicer and XPO5) and splicing factor (SRSF3 and hnRNPA3) expression correlate with increased COVID-19 severity." (PMID 39138195, 2024).
acute myeloid leukemia (1 paper, 2025). Acute myeloid leukemia (AML) is a group of neoplasms arising from precursor cells committed to the myeloid cell-line differentiation. "Similarly, hnRNPA3 may function as a m6A reader protein that recognizes and modulates the alternative splicing of the oncogenic fusion gene AML1/ETO pre-mRNA, thus contributing to the progression of acute myeloid leukemia." (PMID 40344709, 2025).
atherosclerosis (1 paper, 2023). A disease characterized by the build-up of fatty material and calcium deposition in the arterial wall resulting in partial or complete occlusion of the arterial lumen. "Although the senescence phenotype may have deleterious effects on atherosclerosis onset and development, a hnRNPA3 decrease may simply limit SMC proliferation and, in vivo, it may antagonize an environment favoring SMCs to acquire the synthetic migratory phenotype." (PMID 37570694, 2023).
breast carcinoma (1 paper, 2026). "Its strong association with therapy resistance positions HNRNPA3 as both a prognostic biomarker and promising therapeutic target for breast cancer intervention strategies." (PMID 42087895, 2026).
glioma (1 paper, 2021). A benign or malignant brain and spinal cord tumor that arises from glial cells (astrocytes, oligodendrocytes, ependymal cells). "Among them, ARHGAP11A, DRP2, HNRNPA3, KLF10, PAIP1, and RCN1 have not yet been studied in gliomas." (PMID 34434651, 2021).
HIV-1 infection (1 paper, 2015). The type species of lentivirus and the etiologic agent of acquired immunodeficiency syndrome (AIDS). "We find that pseudogene HNRNPA3P6, its parent gene HNRNPA3 and a close paralog of the parent gene HNRNPA1 are under-expressed in HIV-1 infection." (PMID 26426037, 2015).
pneumonia (1 paper, 2024). An acute, acute and chronic, or chronic inflammation focally or diffusely affecting the lung parenchyma, caused by an infection in one or both of the lungs (by bacteria, viruses, fungi, or mycoplasma.). "The age-associated downregulation of Dicer, XPO5, SRSF3, and hnRNPA3 expression in lung tissues is one of the reasons why older individuals are more prone to developing severe pneumonia after SARS-CoV-2 infection than younger ones." (PMID 39138195, 2024). "In summary, N protein leads to autophagic degradation of Dicer, XPO5, SRSF3, and hnRNPA3, inducing DNA damage and proteotoxic stress and eventually causing pneumonia." (PMID 39138195, 2024). "Age-associated downregulation of Dicer, XPO5, SRSF3, and hnRNPA3 expression in lung tissues increases the severity of N protein-induced pneumonia." (PMID 39138195, 2024). "Here, the authors provide evidence that SARS-CoV-2 N protein leads to autophagic degradation of Dicer, XPO5, SRSF3, and hnRNPA3, inducing DNA damage and proteotoxic stress, eventually causing pneumonia." (PMID 39138195, 2024). "Therefore, age-associated downregulation of Dicer, XPO5, SRSF3, and hnRNPA3 expression in lung tissues may render older individuals more prone to developing severe pneumonia after SARS-CoV-2 infection." (PMID 39138195, 2024). "Older mice show lower expression of Dicer, XPO5, SRSF3, and hnRNPA3 in their lung tissues and exhibit more severe N protein-induced pneumonia than younger mice." (PMID 39138195, 2024). "SARS-CoV-2 N protein induces the autophagic degradation of Dicer, XPO5, SRSF3, and hnRNPA3, inhibiting miRNA biogenesis and RNA splicing and triggering DNA damage, proteotoxic stress, and pneumonia." (PMID 39138195, 2024). "Dicer, XPO5, SRSF3, and hnRNPA3 expression was downregulated in the lung tissues of older mice compared with that in younger mice, and N protein induced more severe lung injury and pneumonia in older mice." (PMID 39138195, 2024). "Dicer, XPO5, SRSF3, and hnRNPA3 knockdown increases, while their overexpression decreases, N protein-induced pneumonia’s severity." (PMID 39138195, 2024). "Dicer, XPO5, SRSF3, and hnRNPA3 knockdown in lung tissues led to lung injury and pneumonia, whereas their overexpression partially alleviated N protein-induced pneumonia." (PMID 39138195, 2024). "The effects of anastrozole on the expression of Dicer, XPO5, SRSF3, and hnRNPA3 and pneumonia were also observed in the SARS-CoV-2-infected mouse model." (PMID 39138195, 2024). "Although the expression levels of Dicer, XPO5, SRSF3, and hnRNPA3 were lower in the tissues of old mice than in those of young mice, PJ34 rescued the N-induced downregulation of Dicer, XPO5, SRSF3, and hnRNPA3 and ameliorated N protein-induced pneumonia not only in young mice but also in old mice." (PMID 39138195, 2024). "Dicer, XPO5, SRSF3, and hnRNPA3 knockdown increased the severity of N protein-induced pneumonia." (PMID 39138195, 2024). "Here, we show that SARS-CoV-2 N protein induces the autophagic degradation of two RNAi components (Dicer and XPO5) and two splicing factors (SRSF3 and hnRNPA3), thereby inhibiting miRNA biogenesis and RNA splicing and triggering DNA damage, proteotoxic stress, and pneumonia." (PMID 39138195, 2024). "Moreover, genetic or pharmacological rescue of Dicer, XPO5, SRSF3, and hnRNPA3 expression relieves the N protein-induced DNA damage, proteotoxic stress, and pneumonia." (PMID 39138195, 2024). "Collectively, these results reveal that anastrozole alleviates SARS-CoV-2 N protein-induced pneumonia by promoting Dicer, XPO5, SRSF3, and hnRNPA3 expression." (PMID 39138195, 2024). "Collectively, these results indicate that PJ34 alleviates pneumonia by preventing the N protein-induced downregulation of Dicer, XPO5, SRSF3, and hnRNPA3." (PMID 39138195, 2024).
pneumonia (continued). "Treatment with PJ34 increased the expression of Dicer, XPO5, SRSF3, and hnRNPA3 in SARS-CoV-2-infected lung tissues and ameliorated the pneumonia induced by ectopic N protein expression and SARS-CoV-2 infection." (PMID 39138195, 2024). "Treatment with PJ34 or anastrozole alleviates the N protein-induced DNA damage, proteotoxic stress, and pneumonia by rescuing Dicer, XPO5, SRSF3, and hnRNPA3 expression." (PMID 39138195, 2024). "Here, we found that anastrozole alleviated N protein- or SARS-CoV-2-induced pneumonia by promoting Dicer, XPO5, SRSF3, and hnRNPA3 expression." (PMID 39138195, 2024). "PJ34, a poly(ADP-ribose) polymerase inhibitor, or anastrozole, an aromatase inhibitor, ameliorates N protein- or SARS-CoV-2-induced pneumonia by restoring Dicer, XPO5, SRSF3, and hnRNPA3 expression." (PMID 39138195, 2024). "Furthermore, SARS-CoV-2 infection also led to the downregulation of Dicer, XPO5, SRSF3, and hnRNPA3 in mouse lung tissues, and overexpression of Dicer, XPO5, SRSF3, and hnRNPA3 in mouse lung tissues partially alleviated SARS-CoV-2-induced pneumonia." (PMID 39138195, 2024). "Furthermore, Dicer, XPO5, SRSF3, and hnRNPA3 knockdown exaggerated the N protein-induced DNA damage, apoptosis, cytosolic DNA accumulation, upregulation of IFNβ, IL-6, and NKG2D ligands, and pneumonia." (PMID 39138195, 2024). "Moreover, we found that anastrozole promotes Dicer, XPO5, SRSF3, and hnRNPA3 expression and ameliorates N protein-induced pneumonia not only in young mice but also in old mice." (PMID 39138195, 2024).
cancer (4 papers, 2017 to 2025). A tumor composed of atypical neoplastic, often pleomorphic cells that invade other tissues. "In addition to its effects on cell senescence, differentiation and neurodegeneration, hnRNPA3 is of great interest for its value in cancer." (PMID 35879279, 2022). "Furthermore, hnRNPA3 combined with GPC3 can effectively differentiate between HGDN and eHCC, implying the aptitude of hnRNPA3 to differentially diagnose cancer." (PMID 35879279, 2022). "While the downregulated DEGs in the Control vs. Poly I: C treated group of Gaddi dogs showed pathways highlighting, such as in cancer with NOTCH2, MDM2, and E2F3, the pathway related to RNA metabolism was also enriched for genes such as HNRNPA3 and XPO1." (PMID 40621499, 2025). "Most of the current studies on HNRNPA3 are directed at its function in cancer fields, but the role of HNRNPA3 in virus replication has not been reported." (PMID 38259103, 2024). "Interestingly, the analysis revealed that 7 targets (SF3B1, SF3B3, SNRPA, SNRPE, SNRPF, HNRNPA3 and EFTUD2) are physically interacting proteins within the spliceosome complex, suggesting that JA might regulate the cancer spliceosome to induce tumor-specific cell death." (PMID 28198434, 2017).
tumor (4 papers, 2017 to 2026). "Although there is a lack of information on the exact relationship between HNRNPA3 and tumorigenesis, members of the HNRNP protein family are closely associated with tumor regulation." (PMID 37046429, 2023).
infection (2 papers, 2022 to 2024). The state of being infected such as from the introduction of a foreign agent such as serum, vaccine, antigenic substance or organism. "On the contrary, MOPV infection led to the late (48 h) release of PSMD2, RPS11, HNRNPA3, ATP1A1, TARS1, and PRKAR1A, whereas significantly elevated levels of IGFBP3 were found at both timepoints." (PMID 35337059, 2022).
neuromuscular disease (1 paper, 2014). "Other members of the hnRNP family were recently associated with neuromuscular diseases; hnRNPA3 was found in cytoplasmic inclusions in ALS and FTLD cases caused by a hexanucleotide expansion in C9ORF72 and HNRPDL was identified as a cause of limb-girdle muscular dystrophy 1G." (PMID 25299611, 2014).
HNRNPA3 also shares sentences with these, for which no sentence is quoted: lung carcinoma (2 papers); anemia (1); colon cancer (1); fragile X-associated tremor/ataxia syndrome (1); hereditary hemochromatosis (1); insomnia (1); lymph node metastasis (1); prostate adenocarcinoma (1); vitiligo (1).